IL10 (interleukin 10)
Diseases named in the same sentence as IL10 in open-access papers (continued):
Sharing a sentence is not in itself a finding about the gene and the disease.
periodontitis (continued). "Levels of IL-1β and IL-10 in GCF of patients with chronic periodontitis have been significantly altered in diseased versus nondiseased sites and tended to return to normal values after a 32-week periodontal therapy." (PMID 26977121, 2016). "The ability of IL-10 to modulate key pro-inflammatory cytokines such as IL-1β, TNF-α, and IL-6, along with its interplay with IL-17 signaling and its regulatory effects on osteoclast differentiation and ABL, points to its multifaceted role in the pathophysiology of periodontitis." (PMID 41289041, 2025). "IL-12 and IL-18/IL-10 ratio was not correlated with periodontitis group." (PMID 39080003, 2024). "Within the limitations of this study, the findings suggest that IL-17 and IL-10 could discriminate periodontal health from smoker and nonsmoker's periodontitis; however, much further investigations for validity and reliability are essential." (PMID 37172945, 2024). "From another perspective, some authors reported an IL-10 rise in smoker's periodontitis than nonsmokers,42and attributed it to the ability of smoking to disturb the balance between helper T cells toward a Th2 predominance and thus more of Th2 cytokines as IL-10." (PMID 37172945, 2024). "Finally, we have compared peak breadth distribution within genes positioned by H3K4me3, and we noted a decrease in the average breadth as well as more ‘sharp–narrow’ peaks in patients with NMOSD and periodontitis, which corresponds with TNF-preactivated and IL-10-stimulated neutrophils." (PMID 38745328, 2024). "Moreover, a bi-directional relationship is suggested by several authors because of the increased production of pro-inflammatory cytokines such as IL1B, IL4, IL6, IL10, CBL, and RELA, which are often present in the periodontitis development and CRC carcinogenesis." (PMID 39517401, 2024). "On day 7 after periodontitis induction and treatment administration, blood was drawn from the inferior vena cava, totaling 10 mL, to obtain blood serum for determining the levels of proinflammatory cytokines TNF-α, IL-1β, and anti-inflammatory cytokines IL-10, IL-13 through ELISA examination." (PMID 39539670, 2024). "Since all patients from the MS group were in remission and none of the subjects from the HC group had periodontitis, this may explain the similar expression of IL-10 in the two groups." (PMID 38541692, 2024). "By contrast, we did not identify any variation in IL-10 level according to periodontitis stage." (PMID 39080003, 2024). "The biomarkers have shown good-to-excellent AUC values in discriminating between all smokers and non-smokers periodontitis stages from periodontal health, except for IL-10, which failed to distinguish the smokers and nonsmokers of stage III from the healthy controls." (PMID 37172945, 2024). "According to our findings and prior reports, IL-10 is related to advanced periodontitis; however, it might not have a destructive effect." (PMID 39080003, 2024). "Furthermore, some other studies have shown that IL-10 produced by B cells can alleviate alveolar bone resorption and regulate the local CD4+ T cell population, suggesting that B cells have some potential for regulating periodontitis." (PMID 37226540, 2023). "However, the overexpression of IL-10 agrees with our clinical observation that the IBD patients had no signs of periodontitis." (PMID 34383142, 2022). "Then, the treatment of periodontitis with multi-dose SHED every 7 days can change the expression profile of cytokines in gingival crevicular fluid, with a reduction in the pro-inflammatory cytokines TNF-α, IFN-γ and IL-2, and an increase in the anti-inflammatory molecule IL-10." (PMID 34868054, 2021). "Besides, the existence of elevated cytokines expression comprising pro‐inflammatory and regulatory cytokines such as IL‐1β, interferon (IFN)‐γ, IL‐1 receptor antagonist (RA), IL‐4, IL‐6, IL‐10, IL‐12, TNF‐α, and induced protein (IP)‐10, lead the way to periodontitis’ inflammatory process." (PMID 34272761, 2021).
periodontitis (continued). "However, a negative correlation between the production of BDNF and IL-10 was observed in samples from patients with periodontitis." (PMID 25587209, 2014). "Thus, considering all the GCF samples (from periodontitis patients and controls), the percentage of samples considered below the detection level were 13% for IL-1β, 31% for IL-6, 3% for IL-10 and 5% for TNF-α (data not shown)." (PMID 24944641, 2014). "However, the association of IL-10 and TNF-α SNPs with periodontitis in a subsequent investigation was not confirmed." (PMID 24274085, 2013). "Furthermore, reparative M2-exosomes further deliver IL-10 mRNA to activate the IL-10/IL-10R pathway, simultaneously upregulating IL-10 expression in BMSCs and bone marrow-derived macrophage, which drives BMSC osteogenesis and inhibits osteoclast formation in periodontitis mice." (PMID 41394811, 2025). "Numerous reports have shown that periodontitis could raise the serum pro-inflammatory state, characterized by increased levels of C Reactive Protein (CRP) and pro-inflammatory cytokines (e.g. TNF-α), and decreased levels of anti-inflammatory markers (e.g. IL-10)." (PMID 29422938, 2018). "However, other studies did not support a role of IL-10 SNP in periodontitis." (PMID 24274085, 2013). "Those with periodontitis had a significantly higher rate of cognitive decline, along with elevated levels of the pro-inflammatory cytokines TNF-α and IL-10, although not of IgG against P. gingivalis." (PMID 40231144, 2025). "In our study, we observed higher levels of IL-10 in stage III/IV periodontitis compared to stage I/II (p = 0.047), as well as in grade C periodontitis patients compared to grades A and B (although without statistical significance)." (PMID 39125970, 2024). "Subsequently, the inflammatory cytokines expression levels (interleukin-IL-6, IL-1β, IL-8, and IL-10) in EXO-NET EVs were measured for non-periodontitis and periodontitis." (PMID 39697803, 2023). "The expression levels of four inflammatory cytokines, IL-6, IL-10, IL-8, and IL-1β, were evaluated in salivary EXO-NET EVs of non-periodontitis and periodontitis patients using ELISA." (PMID 39697803, 2023). "Conversely, IL-10 and transforming growth factor-β (TGF-β), for example, derived from Treg cells, can modify innate and adaptive immune responses in periodontitis in a variety of ways, often, but not always, inhibiting immune responses." (PMID 24944840, 2014). "The results indicating a decrease in the levels of the proinflammatory cytokines, IL-1α, -1β and -6, but not IL-10 or TNF-α, in the GCF of patients with chronic periodontitis, confirm the observations of previous studies." (PMID 24944641, 2014). "Likewise, CD25+Foxp3+ Tregs were strikingly diminished in periodontitis lesions with bone resorption compared to healthy gingival tissues, and the correlation between RANKL and IL-10 was negative." (PMID 33149125, 2020). "However, immunoreactivities for IL-10 and TGF-β1 were rarely found in human periodontitis gingival tissues (data not shown)." (PMID 24363500, 2013). "Based on the data evidenced in the group non-diabetic, in which the circulating IL-10 levels were positively correlated with IL-6 and IFN-γ, at baseline, as well as with TNF-α after the treatment ends, we can suggest that a regulatory status was maintained even with the presence of periodontitis." (PMID 39253540, 2024).
Insulin resistance (236 papers, 2011 to 2026). Increased resistance towards insulin, that is, diminished effectiveness of insulin in reducing blood glucose levels. "IL-10 is an anti-inflammatory cytokine associated with M2 macrophages that improves insulitis and insulin resistance in preclinical studies." (PMID 41472730, 2025). "A lower level of the anti-inflammatory IL-10 in the blood has been linked to insulin resistance, metabolic syndrome, and type II diabetes." (PMID 38138954, 2023). "Upon such time, mice exhibited worsening of insulin signaling and the activation of gluconeogenic and lipidogenic pathways, suggesting that IL-10 exerts a protective role for liver insulin resistance associated with steatosis." (PMID 37593740, 2023). "These probiotics have also been associated with a reduction in insulin resistance (IR) and proinflammatory cytokines, as well as a concomitant increase in interleukin-10 (IL-10) and an improvement in fatty liver indices." (PMID 37047729, 2023). "This decrease in IL-10 levels is often observed in patients with PD, and it is associated with insulin resistance." (PMID 30405072, 2018). "Given that IL-10 has been found to protect against diet-induced insulin resistance and to be positively associated with insulin sensitivity, we measured this cytokine in the plasma." (PMID 22470484, 2012). "It has been concluded that high glucose levels in patients with type 2 diabetes could inhibit the suppression of TNF-α by IL-10 because of its disrupted messaging pathway which can cause insulin resistance." (PMID 38164478, 2024). "In obese humans, IL10 expression in WAT was inversely associated with insulin resistance." (PMID 34248663, 2021). "The rs615563, on the other hand, was associated with a lower risk of having central obesity, metabolic syndrome, hyperinsulinemia, insulin resistance, insulin resistance of adipose tissue, low risk of increased alkaline phosphatase >p75, and low risk of having decreased interleukin 10 <p25." (PMID 33925815, 2021). "We also discovered increased insulin resistance in population with allele A. These findings implied that allele A of rs3021094 might increase IL-10 production and GDM susceptibility." (PMID 30873205, 2019). "Indeed, expansion of the Treg compartment in high-fat diet-fed mice was associated with increased levels of IL-10, statistically significant lower blood glucose levels, and trends toward lower insulin resistance and glucose tolerance." (PMID 25157251, 2014). "Furthermore, IL6 is a key factor in the onset and progression of NASH and in the development of insulin resistance, while a relative deficiency of IL10 can be associated with NASH." (PMID 24084730, 2013). "In our research, we analyzed the influence of insulin resistance on epigenetic modification (both at the DNA and histone levels) within the promoter region of the gene encoding IL-10 (IL10) as well as the potential influence of these modifications on IL10 expression." (PMID 35205339, 2022). "Therefore, the association observed between IL-10 and stress hyperglycemia might be hypothetically explained as a counter regulatory response to insulin resistance and stress hyperglycemia induced by acute illness." (PMID 36059840, 2022). "In vitro studies have documented that IL‐10 protects against TNF‐α‐dependent insulin resistance in adipocytes." (PMID 41549047, 2026). "The indirubin, an AhR agonist, induced the secretion of IL-10 and IL-22 by activating AhR to prevent high-fat diet-induced insulin resistance in mice model." (PMID 39944639, 2025). "Adipose tissue-derived stem cells (ADSCs) promoted the expression of IL-10 to ameliorate hyperglycemia and insulin resistance and prevented T2D." (PMID 39944639, 2025). "IL-10 and IL-13 are known to suppress pro-inflammatory cytokine production and play a role in insulin resistance, respectively." (PMID 41221275, 2025).
Insulin resistance (continued). "In fact, it has been reported that IL‐10 prevents diet‐induced insulin resistance both in liver and skeletal muscle, through a reduction in the production of tissue IL‐6 and TNF‐α." (PMID 40207597, 2025). "A clinical study demonstrated that reduced IL-10 levels in these patients correlate with heightened systemic inflammation, increased insulin resistance, and impaired Breg function." (PMID 40370441, 2025). "Reduced IL-10 production by Bregs exacerbates inflammation in adipose tissue, contributing to insulin resistance and worsening disease pathology." (PMID 40370441, 2025). "We found its positive association with BMI, glycated hemoglobin, leptin, insulin, IL-8 and IL-10 levels supporting a galectin-1 interconnection with glucose control, insulin resistance and inflammation." (PMID 40698658, 2025). "Probiotics have been shown to decrease pro-inflammatory cytokines, increase IL-10 levels, alleviate islet damage, and improve insulin resistance." (PMID 40647186, 2025). "Adaptive transfer of B1a cells or IL-10 rapidly improves insulin resistance and glucose tolerance, supporting the protective role of B1a and IL-10 in IR." (PMID 38455510, 2024). "In the lean state, adipose natural B regulatory cells (Breg and B-10), in addition to spleen-derived B-10 and B-1a cells, are known to secrete IL-10 and protect against insulin resistance." (PMID 39606781, 2024). "M2 macrophages release anti-inflammatory cytokines such as the IL-10 and IL-1 receptor antagonists, which help protect against insulin resistance." (PMID 39606781, 2024). "This suggests that the injection of IL-10-treated SVFs into the adipose tissue of diabetic mice suppresses gluconeogenic gene expression and insulin resistance through IL-10/STAT3 signaling in the liver." (PMID 39125659, 2024). "Its anti-inflammatory effects are mediated through the downregulation of IL-6 and TNF-α and the upregulation of IL-10, thereby mitigating chronic inflammation that contributes to insulin resistance and β-cell dysfunction." (PMID 39796549, 2024). "We did not compare the effects of injecting IL-10-treated SVFs with those of injecting IL-10 alone in terms of liver gluconeogenesis and insulin resistance." (PMID 39125659, 2024). "Our data clearly demonstrated that IL-10 treatment modulated the SVFs of the adipose tissue and IL-10-treated SVFs reduced DM-induced insulin resistance and liver gluconeogenesis by enhancing Tregs in the adipose tissue." (PMID 39125659, 2024). "Studies have shown that endogenous IL-10 protects the liver against diet-induced insulin resistance." (PMID 39125659, 2024). "In white adipose tissue, reduced IL-10 led to chronic inflammation, contributing to insulin resistance." (PMID 39274918, 2024). "Our data showed that in cases of severe inflammation, insulin resistance cannot be restored by IL-10 alone, as it was recently reported." (PMID 37026009, 2023). "Several studies have shown that IL-10 has a vital role in suppressing the development of insulin resistance as well as regulating the transcription of thermogenic genes in white adipose tissue." (PMID 37576807, 2023). "Inadequate secretion of cytokines such as TNF-α and IL-10 strengthens insulin resistance in db/db mice, resulting in adipocytes’ increased insensitivity to insulin." (PMID 38202328, 2023). "FGF23 is associated with inflammation through IL-6 (interleukin 6), IL-10 (interleukin 10), and CRP (C-reactive protein) and with symptoms of metabolic syndrome: insulin resistance, visceral obesity, and dyslipidemia." (PMID 38139126, 2023). "WG significantly improved markers of insulin resistance and upregulated jejunal Il10 and Il22 genes." (PMID 37181127, 2023). "The anti-inflammatory IL-10 imparts protection against insulin resistance through its modulation of cytokine production by macrophages." (PMID 37383391, 2023).
Insulin resistance (continued). "In summary, B cells can become involved in inflammation and insulin resistance, among others, by decreasing IL-10 secretion, and activating T cells that produce IFN-γ." (PMID 36262060, 2023). "Reduced systemic levels of IL-10 were associated with the severity of OSA and insulin resistance while VEGF levels were found to be frequently elevated in OSA." (PMID 36983783, 2023). "IL-10, which is involved in the regulation of insulin secretion, β-cell apoptosis, and peripheral insulin resistance, was reduced in the T2DM model." (PMID 37229468, 2023). "On the other hand, an RCT of galantamine successfully reduced serum levels of TNF-α, increased levels of IL-10, and improved insulin resistance in patients with metabolic syndrome." (PMID 35858588, 2022). "Our results demonstrated that UC-MSCs elevated serum IL-10 levels and subsequently promoted macrophage polarization, leading to alleviation of insulin resistance in EAT." (PMID 35313972, 2022). "In our research, we analyzed the influence of insulin resistance on epigenetic modification within the promoter region IL10 gene and the potential influence of these modifications on its expression." (PMID 35205339, 2022). "Pgc-1α was also able to modulate IL-10 expression, improving insulin resistance and hepatic steatosis." (PMID 35326098, 2022). "HFD-fed mice had a higher insulin resistance than NCD mice, while MSCs and IL10-MSCs treatments decreased the HFD-induced insulin resistance (p < 0.001)." (PMID 35715850, 2022). "In the present study, we analyzed the influence of insulin resistance on epigenetic modification in the promoter region of the IL10 gene as well as the potential influence of these modifications on IL10 expression in adipocytes." (PMID 35205339, 2022). "In the human SAT-derived adipocytes, we observed a 3.5-fold increase in IL10 expression in IR cells, compared to control cells after 48 h after insulin resistance induction (p = 0.011), and a 1.5-fold increase after 72 h (p = 0.137)." (PMID 35205339, 2022). "Gut microbiome and microbial products induced the production of interleukin (IL)-10 which improved glucose metabolism and prevented aging-related insulin resistance." (PMID 35185792, 2022). "Patients with severe CAP have inflammatory immune activation (manifested by an increased IL-6 level and IL-16/IL-10 ratio), acquired growth hormone (GH) resistance, and insulin resistance." (PMID 35619955, 2022). "We discovered that the new nutraceutical was able to improve insulin resistance and hepatic steatosis mainly by regulating IL-6, IL-10, and Pgc-1α gene expression." (PMID 35326098, 2022). "We demonstrated that multiple UC-MSC infusions mitigated insulin resistance in EAT of HFD-induced obese mice at least partially by promoting IL-10 production by Treg cells in the spleen." (PMID 35313972, 2022). "The increase in the IL10 expression level in cells with induced insulin resistance, which we observed in the subcutaneous human cell culture in first time point (after 48 h), confirms a previous scientific report." (PMID 35205339, 2022). "The increase in IL10 expression is probably the result of the inflammation processes occurring during the development of insulin resistance in adipocytes." (PMID 35205339, 2022). "Collectively, our data suggest that MKP-2 promotes IGF-1, SDF-1, FKN, and IL-10 signaling to contribute to development of insulin resistance, NAFLD, fibrosis, and inflammation." (PMID 35745205, 2022). "Studies have shown that endogenous IL-10 is a protective factor against diet-induced insulin resistance in the liver." (PMID 35883204, 2022). "Observations in the mouse cell model, as well as in the SAT human cell culture, showed a strong 4.5-fold increase in IL10 expression in IR cells 48 h after the induction of insulin resistance and twofold after 72 h." (PMID 35205339, 2022).